SIRT6 (sirtuin 6)
Diseases named in the same sentence as SIRT6 in open-access papers (continued):
Sharing a sentence is not in itself a finding about the gene and the disease.
metabolic disorders (33 papers, 2016 to 2026). "In view of observations that SIRT6-deficient animals exhibit genomic instability and metabolic disorders and undergo early death, SIRT6 has long been considered a protein of longevity." (PMID 36465178, 2022). "SIRT6 deficiency in mice causes a severe metabolic disorder, which leads to multi‐organ atrophy, premature aging features, and death within 1 month." (PMID 31967391, 2020). "In addition, animal experiments and clinical studies have shown that moderate exercise and calorie restriction (CR) stimulated SIRT6 expression, improving age-related pathological processes such as inflammation, metabolic disorders, and susceptibility to CVDs." (PMID 36465178, 2022). "A reduction in hepatic SIRT6 expression and activity has been reported in metabolic disorders, including MASLD." (PMID 42193040, 2026). "We have previously reported that a high‐fat diet can reverse metabolic disorders and premature aging in SIRT6 KO mice." (PMID 36567449, 2023). "Rosiglitazone and rolipram have been shown to upregulate SIRT6 expression, ameliorating metabolic disorder." (PMID 36465178, 2022). "SIRT1, SIRT6, and SIRT7 are nuclear proteins, and SIRT1 and SIRT6 exert beneficial effects against metabolic diseases." (PMID 36429037, 2022). "This suggests that Sirt6 is a therapeutic target in aging, cardiac disorders, neurodegenerative disorders, and metabolic disorders." (PMID 33442387, 2020). "Chrysophanol and targeted SIRT6 therapy have broad prospects for the treatment of metabolic diseases." (PMID 33274005, 2020). "Deficiency of Sirtuins (SIRT1, SIRT6, and SIRT7) is associated with shortened lifespan and metabolic diseases." (PMID 30574122, 2018). "By contrast, germline or cell-specific overexpression of SIRT1 or SIRT6 were reported to expand lifespan and defense metabolic diseases in insulin-dependent and independent manners." (PMID 30574122, 2018). "Hence, SIRT6 is involved in glucose and lipid metabolism via both direct and indirect means, and is expected to become a therapeutic target in the treatment of metabolic diseases in the future." (PMID 39372420, 2024). "Additionally, our previous studies have shown that high‐fat diets in SIRT6 KO mice can extend their lifespan and reverse metabolic disorders." (PMID 36567449, 2023). "One study found that, in SIRT6 knockout mice, intake of a high-fat diet could reverse metabolic disorders and premature aging, because fatty acids might be a better energy source to switch the physiological mechanisms." (PMID 33920726, 2021). "Additionally, we evaluated chrysophanol's effects, during metabolic disease treatment, dependency on SIRT6 in adipocyte-specific deletion of a SIRT6 mice model." (PMID 33274005, 2020). "Therefore, Sirt6 plays a crucial role in metabolic diseases and neurodegenerative diseases; future studies should be directed in developing genetic and pharmacologic activation of Sirt6." (PMID 33442387, 2020). "Targeting hepatocyte SIRT6 may be useful for treating common metabolic disorders." (PMID 37566087, 2023). "SIRT1 and SIRT6 have beneficial effects against metabolic diseases, but we demonstrate that Sirt7 knockout mice are protected from high-fat-diet–induced obesity, glucose intolerance, and fatty liver, suggesting that SIRT7 deficiency plays a beneficial role in metabolic disorders." (PMID 36012298, 2022). "Future research should focus on whether known SIRT6 activators influence anti-inflammatory activity by contributing to metabolic pathways involving inflammatory cells, which represent common and promising targets in metabolic diseases and inflammatory responses." (PMID 39372420, 2024).
metabolic disorders (continued). "The investigated parameters related to metabolic disorders included sirtuin 1 (SIRT-1), sirtuin 3 (SIRT-3), sirtuin 6 (SIRT-6), irisin (IRS), myostatin (MSTN), peptide YY (PYY), glucagon-like peptide 1 (GLP-1), and dipeptidyl peptidase 4 (DPP-4)." (PMID 39124846, 2024). "Inhibition of SIRT6 by OSS-128167 blocked the expression of thermogenic genes and activation of white fat breakdown, showing that SIRT6/AMPK pathway increase energy consumption, insulin sensitivity and heat production, thereby alleviating metabolic disorders." (PMID 33440786, 2021). "Thus, Sirt6 acts in an autocrine/paracrine manner as a common link between adipocytes and ATM to relay a dynamic interaction in the modulation of metabolic diseases." (PMID 31113929, 2019).
cardiovascular diseases (32 papers, 2016 to 2026). "SIRT6 is closely linked to aging-related cardiovascular diseases due to its involvement in various processes, including oxidative stress, inflammatory responses, autophagy, genome integrity, and telomere homeostasis." (PMID 38186648, 2023). "As sirtuin 6 (SIRT6) is a conserved NAD + dependent protein deacetylase modulating telomeric chromatin, SIRT6 is closely associated with aging and cardiovascular disease." (PMID 36411459, 2022). "On the other hand, SIRT1 and SIRT6 inhibitors have aggravated cardiovascular diseases, which underlines the need for a reliable SIRT1 and SIRT6 activators." (PMID 34650436, 2021). "Our findings linking SIRT6 and telomere integrity in the heart warrant further investigation into the underlying mechanisms and support SIRT6 as a promising therapeutic target for the treatment of cardiovascular diseases." (PMID 28659816, 2017). "Early studies about SIRT6 have focused on the mechanisms of mitochondrial dysfunction related to aging, metabolism, and cardiovascular diseases." (PMID 41362737, 2026). "Cardiovascular diseases (CVDs) progression is significantly modulated by epigenetic mechanisms, particularly through Sirtuin 6 (SIRT6), a key NAD+‐dependent deacetylase in the sirtuin family." (PMID 40810740, 2025). "Altogether, our findings indicate the promise of Sirt6-enriched exosomes as a novel therapeutic strategy in treating ischemia–reperfusion injuries and cardiovascular diseases at large." (PMID 38172884, 2024). "Recent studies have highlighted the significance of Sirt6 in cardiovascular diseases and MIRI due to its antioxidative, anti-inflammatory, and anti-apoptotic properties." (PMID 38172884, 2024). "The protective role of the SIRT family, particularly SIRT1 and SIRT6, in cardiovascular disease has been extensively investigated over the past few decades." (PMID 38186648, 2023). "Here, we summarized the roles of sirtuins in cardiovascular diseases; reviewed recent advances in the understanding of SIRT6 in vascular biology, cardiovascular aging, and diseases; highlighted its therapeutic potential; and discussed future perspectives." (PMID 35855341, 2022). "SIRT3 also plays functional role on vascular biology and atherogenesis, and SIRT6 is a potential therapeutic target for cardiovascular diseases." (PMID 35224092, 2022). "SIRT1, SIRT3, and SIRT6 have been shown to provide protective effects in various cardiovascular disease models, by decreasing inflammation, improving metabolic profiles or scavenging oxidative stress." (PMID 34712151, 2021). "As a promising therapeutic target for cardiovascular diseases, SIRT6 demonstrates potent anti-hypertrophic effect both in vivo and in vitro." (PMID 30670969, 2018). "Reportedly, SIRT6 features prominently in cardiovascular disease." (PMID 36733404, 2023). "Interestingly, several studies have identified other sirtuins (mainly SIRT3 and SIRT6) to provide beneficial effects in cardiovascular diseases and energy metabolism." (PMID 35204314, 2022). "Importantly, SIRT6 in all cell types can repress cardiovascular aging and diseases, suggesting SIRT6 as an ideal target for treating aging-related cardiovascular diseases." (PMID 35855341, 2022). "SIRT6 is directly involved in the regulation of cardiovascular diseases." (PMID 33855020, 2021). "Thus, our working hypothesis in the current study was that reductions in SIRT6 are an independent contributor to increases in histone acetylation and oxidative stress in blood vessels, which could place SIRT6 at the forefront of contributors to age-associated cardiovascular disease." (PMID 34744793, 2021). "Sirt6 provides protective effect on aging-related cardiovascular disorder by activating autophagy." (PMID 34175838, 2021).
cardiovascular diseases (continued). "Sirt6 is one of seven mammalian sirtuins, which plays an important role in cell protection against various stress conditions in cardiovascular diseases, and it is believed that its therapeutic effect may rely on autophagy initiation." (PMID 30993014, 2019). "In addition to SIRT1, SIRT6 protects against inflammation, oxidative stress, and cardiovascular disease." (PMID 30845774, 2019). "SIRT6, a well-studied SIRT family members, plays a critical role in human diseases like cancer, diabetes, inflammation and cardiovascular diseases." (PMID 38186648, 2023). "Taken together, the currently identified SIRT6 activators MDL-800/811 show significant value as candidate drugs for treating aging and aging-related cardiovascular diseases." (PMID 35855341, 2022). "To demonstrate the specificity of miR-135a on Sirt1, we measured the levels of Sirt6, another SIRT family member which has common functions as Sirt1 in stress resistance, vascular aging and cardiovascular disease." (PMID 32335545, 2020).
infection (17 papers, 2012 to 2024). The state of being infected such as from the introduction of a foreign agent such as serum, vaccine, antigenic substance or organism. "However, at 24 hours post-infection (hpi), we observed a loss of SIRT6 recruitment, indicating a potential role of SIRT6 in regulating the expression of Abca1 and Abcg1 during the early stages of infection." (PMID 37871034, 2023). "The observed G9a/SIRT6-dependent accumulation of cholesterol and the related abatement of mycobacterial burden upon their functional loss incited us to determine the impact of G9a and SIRT6 in defining in vivo Mtb burden and associated lung tissue pathology during Mtb H37Rv infection." (PMID 37871034, 2023). "In the converse approach, the infection of islets with AdSirt6 increased mRNA and protein levels of Glut2, GK, and Pdx1 and decreased FoxO1 protein expression, indicating the presence of a causal relationship between Sirt6 and FoxO1-Pdx1-Glut2." (PMID 27457971, 2016). "The signal of the far-red fluorescence protein Katushka2S contained in the LV cassette, alone in the empty group, or together with one of SIRT6 versions (WT, N308K/A313S) was detectable, proving the successful infection." (PMID 39033117, 2024). "Three 3 T-3L1 cell groups were generated by LV-mediated infection: preadipocytes OE an empty vector (preAdiE), preadipocytes OE SIRT6 WT (preAdiWT) and preadipocytes OE SIRT6 N308K/A313S (preAdiCent, for “centenarians”)." (PMID 39033117, 2024). "In summary, our findings suggest that during the early stages of infection, SIRT6 deacetylates H3K9, creating a platform for G9a-mediated demethylation of H3K9, ultimately leading to the transcriptional inactivation of Abca1 and Abcg1." (PMID 37871034, 2023). "To assess if the expression of NRF2-dependent antioxidant genes were dependent on G9a- and SIRT6-dependent cholesterol during H37Rv infection, we used specific siRNAs." (PMID 37871034, 2023). "In the current study, we reveal a previously unrecognized function of SIRT6 in the regulation of intestinal type 2 immune responses to protect against the infection of helminth parasites." (PMID 36057627, 2022). "The number of repressed CCR3+Siglec‐F+ eosinophils and eosinophil marker genes in the mS6KO mice were indeed restored by Ad‐Sirt6 infection." (PMID 34125994, 2021). "Poly(I:C) treatment of wild-type BMDM, resulted in a significant temporal activation of both Nampt and Sirt6, indicating that the observed expression is a host-driven response to infection." (PMID 30886604, 2019). "The expression level of NF-κB responsive gene Il6 was increased in Sirt6-knockdown cells after SeV (agonist of the RLR signaling) infection." (PMID 29686974, 2018). "HUVECs were transfected with SIRT6 siRNA for 48 h, or infected with SIRT6 adenovirus (the multiplicity of infection or M.O.I. 10) for 24 h." (PMID 27249230, 2016). "A MOI of 10 achieved near 100% infection efficiency and was used in subsequent experiments to overexpress Sirt6 in ECs." (PMID 25162034, 2014). "This study demonstrates that in the presence of infection, SIRT6 is a regulator of the COX-prostaglandin pathway in endothelial cells." (PMID 23132960, 2012). "Notably, SIRT6 overexpression mimicked these beneficial effects, whereas infection with recombinant AAV9 carrying SIRT6‐specific short hairpin RNA abrogated them." (PMID 38894630, 2024). "In corroboration, loss-of-function of G9a in vitro and pharmacological inhibition in vivo; or utilization of BMDMs derived from Sirt6−/− mice or in vivo infection in haplo-insufficient Sirt6−/+ mice; hampered host cholesterol accumulation and restricted Mtb burden." (PMID 37871034, 2023). "Further, the induction of G9a and SIRT6 was found to be specific to virulent species of mycobacterium as infection of mouse peritoneal macrophages with the non-pathogenic Mycobacterium smegmatis showed only a weak expression of G9a and Sirt6." (PMID 37871034, 2023).
infection (continued). "Also, significantly less cholesterol was detected by Filipin staining in BMDMs derived from Sirt6−/− mice, even in the presence of Mtb H37Rv infection." (PMID 37871034, 2023). "We found that Mtb induces the expression of G9a and SIRT6, which contribute to epigenetically driven differential expression of cholesterol biosynthesis, uptake, and efflux genes, thereby allowing cholesterol accumulation during infection." (PMID 37871034, 2023). "Interestingly, macrophages silenced for G9a and SIRT6 or for G9a-dependent cholesterol biosynthesis/uptake genes showed a further increase in oxidative stress upon H37Rv infection." (PMID 37871034, 2023). "The observation that Nampt and Sirt6 were coordinately induced in macrophages by immune stimulation, either by infection or the ensuing interferon response, prompted us to test whether NAMPT and SIRT6 exhibit antiviral activity." (PMID 30886604, 2019). "Notably, pharmacological inhibition of NAMPT enzymatic activity or knock-down of Nampt or Sirt6 result in increased viral replication revealing anti-viral roles for these metabolic regulators in infection." (PMID 30886604, 2019). "The presence of several putative immune-gene regulatory TF binding sites, prompted us to investigate whether Nampt and Sirt6 expression was induced by infection." (PMID 30886604, 2019). "Second, p65 colocalizes with SIRT6 in the nucleus after infection with DENV." (PMID 29686974, 2018). "Interestingly, Sirt6−/+ infected macrophages treated with G9a inhibitor (BIX-01294) showed further decrease in cholesterol accumulation upon H37Rv infection, indicating a collegial role of G9a and SIRT6 in driving Mtb H37Rv infection-induced cholesterol accumulation." (PMID 37871034, 2023). "In this study, we have investigated the role of SIRT6 in the regulation of intestinal ILC3 function under steady state and during infection and inflammation." (PMID 39253083, 2024). "Similar to Nampt, mCMV infection of wild-type BMDM significantly induced, albeit at a lower level, the expression of Sirt6 expression peaking downstream of Nampt." (PMID 30886604, 2019). "Ad-SIRT6 infection significantly reduced the protein expression of BNP, suggesting that SIRT6 protects the cardiomyocytes against PE-induced hypertrophy." (PMID 30670969, 2018). "Our results indicate that SIRT6 binds to promoter region of TNFSF4 under basal conditions, which was increased upon infection with SIRT6 adenovirus." (PMID 27249230, 2016). "We observed that when ECs were infected with adenovirus at multiplicity of infection (MOI) from 1 to 30, Sirt6 protein increased in a dose-dependent manner." (PMID 25162034, 2014). "However, the contribution of the other nuclear Sirtuin, i.e., SIRT6, during infections, specifically mycobacterial infection, has not been addressed so far." (PMID 37871034, 2023). "To assess for any alteration in cell viability due to siRNA treatment in the infection scenario, we performed MTT assay at 48hpi with and without G9a or SIRT6 knockdown using specific siRNAs and did not observe any significant difference in cell viability." (PMID 37871034, 2023).